SOX10 (SRY-box transcription factor 10)
Diseases named in the same sentence as SOX10 in open-access papers (continued):
Sharing a sentence is not in itself a finding about the gene and the disease.
melanoma (continued). "SOX10 was also found to regulate immunogenicity in melanoma through IRF4 (interferon regulatory factor 4)/MUM1, another transcription factor discovered in our dataset." (PMID 35052351, 2021). "In contrast, the top SFPQ-enriched mRNA transcripts in melanoma cells were generally associated with disease progression, such as AMIGO2, MAGEA3, MAGEA1, and the transcription factor, SOX10." (PMID 34218270, 2021). "FTO expression is regulated by autophagy pathway and nuclear factor kappa B pathways and can be induced by metabolic stress; the FTO protein itself regulates the expression of known melanoma-related genes encoding PD-1 (PDCD1), CXCR4, and SOX10." (PMID 34105069, 2021). "Among these SOX10-positive cells, lgCMN showed much higher expression of P16 than that in melanoma and normal skin tissues; however, the proliferative marker Ki67 exhibited low expression in lgCMN tissues." (PMID 34912899, 2021). "ERK-mediated phosphorylation regulates SOX10 SUMOylation in melanoma and activation of the ERK MAP kinase pathway leads to Elk-1 deSUMOylation followed by loss of HDAC2-mediated repression." (PMID 34356679, 2021). "This study aimed to investigate the diagnostic and prognostic utility of the conventional pan-melanoma cocktail members (HMB-45, melan-A and tyrosinase), in conjunction with SOX10 and SOX11 immunohistochemical (IHC) expression." (PMID 33801642, 2021). "The number of CD40+SOX10+ melanoma cells increased to 103 post BRAF treatment in the one tumor that did not have CD40+SOX10+ cells prior to BRAF inhibitor treatment." (PMID 34092233, 2021). "Immunostaining was positive for Melan A, HMB45, S-100 protein, and SRY-box transcription factor 10, and the final diagnosis was malignant melanoma of the esophagogastric junction, with regional lymph node metastases." (PMID 34882298, 2021). "Immunostaining was positive for Melan-A, HMB45, S-100 protein and SRY-box transcription factor 10, and the patient was diagnosed with malignant melanoma of the esophagogastric junction with regional lymph node metastases." (PMID 34882298, 2021). "Since DIRC3 expression is negatively correlated with both MITF and SOX10 levels, its expression increases in invasive MITFlow melanoma cells." (PMID 34638331, 2021). "The study also identified FRA1 as a key molecule acting downstream of UBE2N to maintain the activity of the MEK/FRA1/SOX10 signaling cascade and promote the malignancy of melanoma." (PMID 34199813, 2021). "Microphthalmia-associated transcription factor (MITF) is found to promote expression of metabolic genes in melanoma and also has a role alongside SOX10 in regulating target genes." (PMID 34249897, 2021). "The different expression levels of SOX10 have been reported to play an important role in melanoma (high expression) and colorectal (low expression) cell lines." (PMID 33507915, 2021). "It is difficult to separate its function in melanoma plasticity entirely from its various upstream regulators including SOX10, PAX3, and FOXD3 among others, as they are tightly connected." (PMID 34071193, 2021). "We used ATAC-Seq analysis of multiple zebrafish melanoma tumors to identify recurrently open chromatin domains surrounding and within the sox10 locus as putative enhancers." (PMID 34099848, 2021). "We next conducted 6-color (hematoxylin, CD40, CD80, CD11c, CD8 and SOX10) multiplex IHC staining on the section of tumors from melanoma patients treated with BRAF inhibitor." (PMID 34092233, 2021). "Previous studies demonstrated the essential role of SOX10 in the pathogenesis of nevi and melanoma in both mice and humans by regulating cell proliferation and survival of melanocytic cells." (PMID 34526609, 2021). "UBE2N knockdown resulted in the increased expression of epithelial markers, including E-cadherin, p16, and MC1R, and decreased expression of melanoma malignancy markers, such as SOX10, nestin, and ABCB5." (PMID 34199813, 2021).
melanoma (continued). "We have previously demonstrated that Sox10, a neural crest transcription factor, plays a crucial role in the development and maintenance of giant congenital melanocytic nevi and melanoma." (PMID 32238882, 2020). "Concordantly, the genetic ablation in Tyr::NrasQ61K mice demonstrated that Sox10 is required for melanoma formation and proliferation, survival, and tumor maintenance." (PMID 32878000, 2020). "SOX10 is a transcription factor that is crucial in neural crest development and we have recently identified it as a novel promising candidate for melanoma treatment." (PMID 32238882, 2020). "To this end, we performed interaction mass spectrometry (MS) using whole cell extracts (WCE) isolated from the M010817 primary melanoma culture mixed with recombinant SOX10 protein in different ratios." (PMID 32238882, 2020). "Of note, MITF, with which SAMMSON is co-amplified at 3p13-3p14, is a transcriptional regulator of lncRNA DIRC3, which is disrupted by balanced translocations in renal carcinoma and suppressed by SOX10 in melanoma cells (see Translocations)." (PMID 33329688, 2020). "Melanoma cells depend on SOX10 for survival, and SOX10 haploinsufficiency prevents or even reverts melanoma formation." (PMID 32238882, 2020). "In melanoma cells, stable SOX10 knockout contributes to G1 phase arrest and the reduced expression of MITF and p21 but elevates p27." (PMID 33344444, 2020). "We have previously shown that SOX10 is expressed in one hundred percent of primary human melanoma samples and that its expression is crucial for melanoma initiation, but also maintenance of established melanomas." (PMID 32238882, 2020). "We further used CEN‐tools to discover and experimentally validate an association between the skin‐specific gene SOX10 and the SRF TF downstream of MAPK signalling in malignant melanoma." (PMID 33073517, 2020). "An interesting example of the role of SOX10 in melanoma is its promotion of the formation and maintenance of giant congenital naevi." (PMID 33024276, 2020). "Next, we performed western blot analysis in several early passage melanoma cultures derived from patient biopsies to analyze effects of MAPK-pathway suppression on SOX10 expression levels in vitro." (PMID 32238882, 2020). "Another study has reported that UBE2N promotes melanoma growth via MEK/FRA1/SOX10 signaling hence proving the role of UBE2N as a potential biomarker for PCa." (PMID 32322560, 2020). "We therefore assessed next the phenotypic consequences of reducing SOX10 protein levels by activating WNT signaling in melanoma cells in vitro." (PMID 32238882, 2020). "In a search for pharmacological inhibitors of SOX10, we performed a mass spectrometry-based screen in human melanoma cells." (PMID 32238882, 2020). "In summary, SOX10 plays a considerable role in the survival, proliferation, metastasis, apoptosis of melanoma cells, and melanoma diagnosis." (PMID 33344444, 2020). "Three independent inhibitors of GSK3α/β (CHIR99021, LY2090314, and AZD1080) inhibited SOX10 protein levels in a panel of human melanoma cell cultures." (PMID 32238882, 2020). "In our previous work, we have unambiguously demonstrated that Sox10 is indispensable for melanoma initiation and maintenance." (PMID 32238882, 2020). "In a mouse model of giant congenital naevi, Sox10 haploinsufficiency was shown to inhibit Nras(Q61K)-driven congenital nevus and melanoma formation." (PMID 33024276, 2020). "As a consequence of β-catenin knockdown in M111031 melanoma cultures, the suppression of SOX10 protein expression upon CHIR99021 treatment was fully rescued." (PMID 32238882, 2020). "This study’s findings were also supported by the fact that in human patients, virtually all congenital naevi and melanomas were SOX10 positive." (PMID 33024276, 2020). "In order to analyze these contradictory assertions, we further investigated the role of canonical WNT signaling in SOX10 regulation in melanoma." (PMID 32238882, 2020).
melanoma (continued). "Numerous studies have suggested that SOX10 is highly expressed in melanoma, breast cancer, bladder cancer, ovarian and epithelial tumors, whereas its tumorigenic roles have not been clearly elucidated yet." (PMID 33344444, 2020). "Previous studies revealed that SOX10 played an important role in melanoma cell survival, proliferation, and metastasis." (PMID 32620903, 2020). "In conclusion, two independent strategies of motif analysis suggest conservation of TF binding sites for known melanoma master regulators, with conserved SOX10, MITF, TFAP2A, and ETS TF family motif enrichment in MEL enhancers across all six studied species." (PMID 32732264, 2020). "Depleting FTO promotes the degradation of downstream genes PD-1, CXCR4, and SOX10 in an m6A-dependent manner, thereby sensitizing patients with melanoma to anti-PD-1 checkpoint blockade therapy." (PMID 33292526, 2020). "Collectively, these studies support a prominent role for SOX10 in the initiation and progression of melanoma." (PMID 33024276, 2020). "The data presented here demonstrate that the canonical WNT signaling is involved in fine-tuning SOX10 protein levels in melanoma." (PMID 32238882, 2020). "Another interesting example of a transcription factor with important roles in melanoma is the transcription factor SR-BOX 10 (SOX10), which is characterized by a DNA-binding motif known as the high mobility group (HMG) domain." (PMID 33024276, 2020). "The binding distribution of MITF coincides with DNA motifs of TFs involved in melanoma development such as SOX10, MITF, AP-1, TEAD and others." (PMID 32605315, 2020). "Immunocytochemical analysis demonstrated that treatment with CHIR99021 strongly diminished SOX10 protein expression levels in our panel of primary melanoma cultures." (PMID 32238882, 2020). "We used immunostainings to determine the PTEN protein status and utilized SOX10 as a melanoma cell marker." (PMID 32245160, 2020). "In this follow up study, we set out to identify agents to pharmacologically inhibit SOX10 protein in melanoma." (PMID 32238882, 2020). "Not all predicted MEL enhancers were in fact active, as MITF binding seems to be required to activate SOX10-dependent melanoma enhancers." (PMID 32732264, 2020). "Other tumors on the differential, metastatic lung cancer, mesothelioma, melanoma, and primary adrenal gland tumor, were excluded by negative staining of tumor cells for TTF-1, napsin, calretinin, WT-1, pan-melanoma, SOX10, and synaptophysin." (PMID 32983683, 2020). "Taken together, we provide evidence that activation of canonical Wnt signaling has a profound effect on melanoma growth and is able to counteract Sox10-dependent melanoma maintenance both in vitro and in vivo." (PMID 32238882, 2020). "SOX9 is expressed in postnatal melanocytes and can induce expression of SOX10 melanocyte target genes in B16 melanoma cells." (PMID 33424631, 2020). "We demonstrate that inhibitors of glycogen synthase kinase 3 alpha/beta (GSK3α/β) efficiently abrogate SOX10 protein in human melanoma cells in vitro and in melanoma mouse models in vivo." (PMID 32238882, 2020). "This study also showed that the depletion of SOX10 sensitized BRAF-mutant melanoma cells to BRAF inhibitors." (PMID 33024276, 2020). "Similar to the results in nude mice, Tomato+ cells in these tumors were positive for melanoma markers such as Sox10 and heterogeneously expressing melanocytic markers Dct and pigment, as well as neuronal markers Tubb3 and Nestin." (PMID 31685822, 2019). "Repression of SOX10 expression was also suggested in melanoma cells which were upregulating ID3 after vemurafenib short-term stimulation." (PMID 31118886, 2019). "E-box and SOX motifs are recognized by the lineage-determining factors MITF and SOX10, respectively, which are essential for melanocyte development and differentiation, normal melanocyte function, and melanoma initiation and proliferation." (PMID 31399133, 2019).
melanoma (continued). "SOX10 levels were higher in all melanoma cell lines than in normal human melanocytes (HEMa-LP), whereas SOX9 expression was low in all these cell lines." (PMID 30642390, 2019). "Another study showed that SOX9 and SOX10 play antagonistic functions in melanoma cells as demonstrated by upregulation of SOX9 expression, which contributed to the pro-apoptotic response induced by SOX10 loss-of-function." (PMID 30642390, 2019). "In contrast, elevation of SOX9 expression is highly effective in restoring melanoma invasiveness in SOX10 KD cells." (PMID 30642390, 2019). "Consistently, the downregulation of SOX10 in untreated melanoma cells was effective in reducing tumour growth, but SOX10 depletion, in treated melanoma cells, led to resistance, and unresponsiveness, to vemurafenib." (PMID 31416288, 2019). "We observed a substantial decrease in viability for both melanoma cell lines after SOX10 knockdown with three of three tested siRNAs, while SOX9 knockdown did not lead to an apparent decrease in cell viability." (PMID 30683138, 2019). "Histologic analysis of the biopsies revealed extensive expression of Sox10 identifying melanoma tumor tissue." (PMID 31703593, 2019). "A study integrating data from transcriptome, open chromatin and histone modification maps of melanoma cultures identified SOX10/MITF as regulator of the proliferative state and AP-1/TEAD as regulator of the invasive state." (PMID 31118886, 2019). "(2018) found that overexpression of SOX10 promoted melanoma cell proliferation and chemotherapy resistance both in vitro and in vivo, and was associated with poor overall survival." (PMID 30499222, 2019). "Recently, the involvement of SOX10 in melanoma drug resistance was reanalyzed at the single cell level." (PMID 31118886, 2019). "Lastly, SOX10 or high SOX9 expression mediates melanoma cell migration through the NEDD9-regulated focal adhesion dynamics and Rho GTPase signaling." (PMID 30642390, 2019). "Although the SOX10-regulated lncRNA SAMMSON is co-amplified with MITF in melanoma, our understanding of how MITF-SOX10 drive melanocyte and melanoma biology, and how much of their activity is mediated by lncRNAs is largely unexplored." (PMID 31881017, 2019). "Recently, SOX10 has also been shown to regulate sensitivity to BRAF inhibitors in melanoma through compensatory mechanisms." (PMID 31416288, 2019). "The expression level and activity of SOX10 was also demonstrated a few years ago, to regulate melanomagenesis and metastases formation in different melanoma mouse models." (PMID 31118886, 2019). "In the second study, SOX10 haploinsufficiency in Tyr::NrasQ61KINK4a−/− mice counteracted melanoma formation." (PMID 31118886, 2019). "Compensatory upregulation of SOX9 expression in SOX10-inhibited melanoma cells reduced growth and migratory capacity, partly due to elevated expression of cyclin-dependent kinase inhibitor p21 and lack of NEDD9 induction." (PMID 30642390, 2019). "Complete ablation of SOX10 in melanoma cells induces growth arrest and senescence, and consistent with this finding SOX10 protein was partially reduced by all 6 shSOX10-expressing cell lines." (PMID 31399133, 2019). "In agreement with this notion, transcription factors SOX9 and SOX10 play important roles in neural crest specification and migration but are also involved in melanoma development." (PMID 30642390, 2019). "SOX10 or high SOX9 expression regulates melanoma mesenchymal migration through the NEDD9-mediated focal adhesion dynamics and Rho GTPase signaling." (PMID 30642390, 2019). "By contrast, the occult micrometastasis contained only few SOX10+ Melan A- melanoma cells which were scattered within a dense infiltrate of T cells, including a prominent population of CD103+ CD8+ T cells resembling tissue-resident memory T (TRM) cells." (PMID 31885869, 2019).
melanoma (continued). "Consistently, previous studies demonstrated an essential role for SOX10 in the pathogenesis of melanoma in both mice and humans by promoting initiation, proliferation, survival, and invasion." (PMID 30642390, 2019). "A previous report revealed that SOX10 transactivates MIA expression through its promoter to induce invasive capacity of melanoma cells." (PMID 30642390, 2019). "The MITF and SOX10 transcription factors regulate the expression of genes important for melanoma proliferation, invasion and metastasis." (PMID 31881017, 2019). "MITF expression is controlled in part through the action of SOX10, and together MITF-SOX10 co-occupy several thousand binding sites on chromatin to control key gene regulatory networks governing melanocyte development and melanoma." (PMID 31881017, 2019). "In the first study, it was showed that SOX10 is required for proliferation of melanoma tumor cell and that SOX10 haploinsufficiency reduces melanoma initiation in the metabotropic glutamate receptor 1 [Grm1(Tg)] transgenic mouse model." (PMID 31118886, 2019). "AlamarBlue, transwell invasion and colony formation assays in melanoma cell lines were conducted to investigate the epistatic relationship between SOX10 and NEDD9, as well as the effects of graded SOX9 expression levels." (PMID 30642390, 2019). "It was shown that downregulation of FBXW7 in melanoma leads to increased MITF-mediated dysregulation of oxidative phosphorylation and increased SOX10 mediated migration of melanoma cells." (PMID 31416288, 2019). "Consistently, as demonstrated in the functional assays, we found NEDD9 expression is regulated by SOX10 and mediates its metastatic functions in melanoma cell lines." (PMID 30642390, 2019). "High SOX9 expression was predominantly detected in patients with distant melanoma metastases whereas SOX10 was present in the different stages of melanoma." (PMID 30642390, 2019). "Here we demonstrate that SOX10 is expressed in melanocytic nevus, primary cutaneous, and invasive melanomas where SOX9 exhibits unique but overlapping expression with SOX10." (PMID 30642390, 2019). "To explore the immune context more broadly we developed a pan-immune OPAL panel comprising CD3 (T cells), CD20 (B cells), CD68 (macrophages), CD11c (likely dendritic cells), SOX10 (melanoma) and DAPI (cell nucleus)." (PMID 30042403, 2018). "To compare our TEAZ-based tumors to the more traditional embryo injection models, we performed immunohistochemistry of the melanomas using antibodies against SOX10, BRAFV600E and phospho-ERK." (PMID 30061297, 2018). "We previously showed that most melanomas, of both fish and human origin, overexpress a neural crest transcriptional program typified by crestin and sox10, making the latter gene particularly relevant for human melanoma." (PMID 30061297, 2018). "Aside from its important roles in melanoma, SOX10 is also a key regulator of the neural crest development." (PMID 29295999, 2018). "In agreement with previous models, we find that both the TEAZ melanomas and embryo injection transgenics have high levels of SOX10 protein expression." (PMID 30061297, 2018). "The impact of SOX10 depletion on melanoma cell proliferation and apoptosis was then analyzed by MTT assay and annexin V/PI staining respectively." (PMID 29295999, 2018). "To test this, we evaluated the ERBB3/AKT signaling and vemurafenib-induced apoptosis in melanoma cells depleted of SOX10." (PMID 29295999, 2018). "Composite images were analyzed using inForm® software to define cells as either melanoma (SOX10+) or T cells subsets (CD3+CD4+, CD3+CD8+, CD3+CD4+FoxP3+, CD3+ CD4−CD8−)." (PMID 30042403, 2018). "Using the tissue segmentation function, the tumor region was defined by SOX10+ melanoma cells, and the tumor stroma region comprised SOX10− cells." (PMID 30042403, 2018). "SOX10 is also highly expressed in melanoma tumors, and SOX10 expression increases with tumor progression." (PMID 29315345, 2018).